GPC3 (glypican 3)
Diseases named in the same sentence as GPC3 in open-access papers (continued):
Sharing a sentence is not in itself a finding about the gene and the disease.
tumor (continued). "In order to further explore the possible mechanism of the anti-tumor effect of the Ad-IL-12/GPC3 vaccine, we first determined the DCs induced in the splenic cells of immunized animals." (PMID 36139670, 2022). "We did not observe any indication of toxicity or off-target expansion of BOXR1030 in normal mouse tissues, while target-specificity of BOXR1030 was observed with expansion in the GPC3+ tumor tissues." (PMID 35507536, 2022). "Results show that elimination of this specificity significantly inhibited the anti-tumor effects related to Ad-IL-12/GPC3." (PMID 36139670, 2022). "The anti-tumor efficacy of NK-92/9.28.z cells has been confirmed in many HCC xenografts with different GPC3 levels." (PMID 35251989, 2022). "GPC3 was significantly down-regulated in tumor tissue in all data sets, while NMI was significantly up-regulated." (PMID 35710585, 2022). "This is suggested from previous data where 89Zr-labelled ERY974 uptake was observed both in the tumour through the GPC3 arm and in the lymphoid tissues through the CD3 arm in a huNOG model." (PMID 36071036, 2022). "This co-immunization in our study promoted the immunogenicity of HCC-specific antigen-GPC3 and efficiently suppressed tumor development of HCC." (PMID 36139670, 2022). "A study in patients treated with RFA or TACE showed that tumor-associated antigens (glypican-3, NY-ESO-1, and MAGE-1)-specific CD8+ T cell responses suppress the recurrence of HCC, and that c-TACE-induced tumor-specific response." (PMID 35884392, 2022). "GPC3-specific CAR-T membrane vesicles were used to wrap IR780-loaded mesoporous silica nanoparticles for tumor targeting and photothermal therapy." (PMID 35874757, 2022). "In a patient with advanced hepatocellular carcinoma, the tumor disappeared completely after 30 days of injecting anti-glypican-3-7 × 19 CAR-T cells at the tumor site." (PMID 36142322, 2022). "After combined immunization, compared with Ad-IL-12 or Ad-GPC3 alone, the numbers of immune effector CD 8+ T cells and dendritic cells were increased in the tumor, indicating that there was a synergistic effect in stimulating immunity." (PMID 36139670, 2022). "A recent study constructed two types of CAR T-cells targeting different epitopes of GPC3 and found that both human YP7 CAR T-cells and 32A9 CAR T-cells possess GPC3-specific anti-tumor functions and inhibit tumor growth under in vitro and in vivo settings." (PMID 36613878, 2022). "Higher expression levels of both antigens, GPC3 and PD-L1, were found in the tumor treated with Combo compared with bispecific treatment." (PMID 35317524, 2022). "GPC3 can be found in the circulation and tumor surroundings due to its release from the cell surface, influencing the efficiency of anti-cancer therapy, which specifically targets these antigens." (PMID 36613878, 2022). "Surprisingly, these CAR-T cells eliminated the tumor completely 30 days after intratumor injection in a patient with advanced GPC3+ HCC in a phase I clinical trial (NCT03198546)." (PMID 36093115, 2022). "Compared to embryos engrafted with scramble small interfering RNA (siRNA)-transfected SY5Y, GPC3 siRNA-transfected cells formed tumor masses almost exclusively outside the proximal and distal sympatho-adrenal (SA) territories." (PMID 36240740, 2022). "For further characterization of PHCs, the expression of the following HCC-specific tumor markers was investigated: GPC3, SPINK1, SPP1 and KPNA2." (PMID 36077764, 2022). "Based on the canonical marker gene expression, 3,085 cells were annotated as tumor cells (GPC3, EPCAM, AFP, ALB, DLK1), while 18,365 cells were designed as non-tumor cells." (PMID 35860547, 2022). "In this single-arm, open-label, first-in-human phase I trial (NCT03980288), Fang and colleagues investigated the safety and anti-tumor activity of autologous 4G-CAR-GPC3 T-cells for patients with GPC3+ heavily pretreated advanced HCC." (PMID 36139683, 2022).
tumor (continued). "Glypican-3 (GPC3) displays diverse biological roles regarding tumor progression in a cell- and tissue-specific manner." (PMID 36358747, 2022). "Glypican-3 (GPC3) is an oncofetal tumor antigen that is an attractive target for CAR T cell therapy due to its highly restricted expression on normal tissue and high prevalence in several adult and pediatric solid tumors." (PMID 35507536, 2022). "Compared with the control immunization group, the Ad-IL-12/GPC3 immunization group showed a significant tumor growth inhibition effect, which was confirmed by the reduced tumor volume and the increased tumor inhibition." (PMID 36139670, 2022). "In particular, NPs coated with anti-GPC3 targeting agents showed great specificity for HCC tumor cells, with the consequent improvement in imaging and drug delivery both in vitro and in vivo compared to the non-targeted counterparts and free drugs." (PMID 36077433, 2022). "The therapeutic effect of the vaccine of glypican-3 and interleukin 12 mainly depends on the anti-tumor effect of CD 8+ T cells mediated by dendritic cells." (PMID 36139670, 2022). "Evaluation of 3rd generation GPC3-CAR-T in a patient derived xenograft (PDX) HCC model demonstrated a reduction in tumour burden compared with CD19-CAR-T controls." (PMID 35158772, 2022). "A pilot study (UMINCTR: 000005093) confirmed lymphocyte tumor infiltration by after vaccination with the GPC3 peptides." (PMID 35251989, 2022). "On the other hand, miR-4510 was considered to be a tumor suppressor as it suppressed the Wnt/β-catenin pathway by targeting the glypican-3 (GPC3) oncogene, thereby decreasing HB cell line and HuH6 cell viability." (PMID 35179516, 2022). "Taken together, the results show that modifying the strength of GPC3-Unc5 interaction determines cancer cell migration properties and tumor targeting in the model presented." (PMID 36240740, 2022). "The high expression of GPC-3 in tumor tissues makes it an ideal target for the imaging and treatment of HCC." (PMID 35624643, 2022). "GPC3 CAR T cells were found to eliminate GPC3-positive HCC cells in mouse models, and a phase I clinical trial demonstrated its safety, as well as some early signs of anti-tumor activity of GPC3 CAR T cells in patients with advanced HCC." (PMID 36291797, 2022). "Last but not least, a few studies have demonstrated that the 124I-codrituzumab compound, an antibody targeting glypican 3 (a cell-surface glycoprotein overexpressed in cancerous tissue), is able to detect tumor localization in most patients with HCC." (PMID 35563414, 2022). "Glypican-3 is a cell membrane-anchored proteoglycan, while agrin is present in the basement membranes of tumor vasculature, bile ducts, and the portal area." (PMID 35186754, 2022). "GPC3‐ENG MSCs express CD80 and 41BBL, which activate human T cells to produce IL2 in an antigen‐dependent manner and facilitate the proliferation of T cells, thereby killing the GPC3+ tumor cells." (PMID 34981659, 2022). "Although the anti-GPC3 antibody was used to block the signal transduction pathway to suppress tumor cells and showed good tolerance, it is almost impossible to eliminate the tumor in the mouse model." (PMID 36139670, 2022). "In an in vivo study on HepG2 tumor-bearing mice, tumor accumulation of the labeled peptide was observed, which was higher compared to the accumulation in GPC3-low-expressing tumors." (PMID 36077433, 2022). "This was combined with an scFv/CD28 co-stimulatory molecule targeting glypican-3 for increased efficacy towards tumor cells." (PMID 35840635, 2022). "GPC3 actively regulates HCC tumor growth, and its expression is related to a poor clinical prognosis of HCC." (PMID 35248060, 2022).
tumor (continued). "It was able to specifically bind GPC3-expressing patient-derived xenograft tumor and accumulate at the tumor mass, with minor uptake in the heart, brain, lungs, muscles, and bones." (PMID 36077433, 2022). "The results showed significant findings where GPC3 was more frequently expressed in tumours that tested positive for hormone receptors AR (11.4%, 15 cases), ER (14.6%, 14 cases), and PR (11.4%, 13 cases)." (PMID 36676710, 2022). "An MRI-detection method for HCC was developed, based on the presence of high concentrations of AFP and glypican-3 in the cytoplasm and on the surface of tumor cells, respectively, compared to healthy cells." (PMID 35683190, 2022). "Glypican-3 is a typical marker of hepatocellular carcinoma, detected not only in the tumor cells but also in the circulation." (PMID 35186754, 2022). "Conversely, although GPC3 was detected in a fraction of tumor cells, its expression was more frequent (29%) in fibroblastic cells of the tumor microenvironment." (PMID 36240740, 2022). "A peptide vaccine prepared from GPC3 was efficacious and safe in promoting tumor infiltration by cytotoxic T cells." (PMID 35686237, 2022). "AFP-based vaccines were used in earlier trials and have since expanded to other tumor antigens such as GPC3 and hTERT." (PMID 35433430, 2022). "As our research shows, the tumor volume and weight of the animals immunized with Ad-GPC3 were reduced." (PMID 36139670, 2022). "The drug vehicle control mAKT/NRAS group developed HCC tumors as judged by H&E staining, histology and IHC staining with tumor markers beta-Catenin and Gpc3, with a mean survival time of 70 days." (PMID 35547764, 2022). "Bispecific antibodies are designed to recognize and bind specific tumor-associated antigens (e.g. AFP, GPC3) and effector cell receptors (e.g. CD3, CD28) in order to initiate tumor cytotoxicity." (PMID 35433430, 2022). "GPC3 mRNA and protein expression was also assessed in primary human tumor samples for selected indications." (PMID 35507536, 2022). "In those conditions, mRNA expression of CSC (Cd133, Epcam and Aldh), of pluripotency (Klf4) and of tumor cell (Gpc3 and Afp) markers were found significantly induced by IL-17 when compared to those from control non-treated LPCs." (PMID 35342340, 2022). "This suggested that the probe bound closely via its targeting peptide to GPC3 on the cancer cell surface and accumulated in large amounts in the tumor." (PMID 35331259, 2022). "Gan and colleagues increased sorafenib delivery using polymeric NPs coated with an anti-GPC3 antibody promoting cellular apoptosis and in vivo tumor growth inhibition." (PMID 36077433, 2022). "We found significantly upregulated CDCA2 expression in HCC, which was correlated with higher clinical stage, tumor grade and Glypican-3 (+)." (PMID 35694386, 2022). "In the subcutaneous tumor model, Ad-IL-12/GPC3 vaccine was injected into muscles three times to evaluate its therapeutic effect." (PMID 36139670, 2022). "These values were used to calculate accuracy, sensitivity, specificity and precision of GC33 staining for GPC3 compared to comparator 1G12 staining in tumor specimens for the purposes of GC33 assay validation." (PMID 35937502, 2022). "These CAR NK cells showed effective cytotoxicity against GPC3-positive tumor cells both in vitro and in vivo and prolonged the survival of CCCO mice without any systemic toxicity and tumorigenicity." (PMID 36428748, 2022). "Freshly isolated cells were additionally characterized for specific mRNA expression of tumor (GPC3, SPINK1, SPP1, KPNA2) and fibroblast (COL1A2, TWIST2, FGF7) marker genes using RT–qPCR." (PMID 36077764, 2022). "Glypican-3 (GPC3) is an oncofetal tumor antigen that is an attractive target for chimeric antigen receptor (CAR) T cell therapy due to its highly restricted expression on normal tissue and high prevalence in several adult and pediatric solid tumors." (PMID 35937502, 2022).
tumor (continued). "The absence of evidence of mucus secretion by Alcian blue staining and the positivity of tumor cells with anti-Hepar or glypican-3 antibodies confirm the diagnosis of HCC." (PMID 36661679, 2022). "In contrast, ERY974 produced rare to occasional staining pattern in SK-pca31a xenograft tumor (low GPC3 expression) and weak to strong staining pattern in SK-pca13a xenograft tumor (moderate GPC3 expression)." (PMID 35853994, 2022). "Immunohistochemically, the tumor expressed glypican-3 (GPC3), SALL4, broad-spectrum keratins (AE1/AE3) and alpha-fetoprotein (AFP)." (PMID 35027045, 2022). "In this second generation CAR T cells, PD-1 is disrupted via CRISPR/Cas9 to enhance the anti-tumor activity of GPC3-CAR T cells against HCC." (PMID 34071188, 2021). "In our study, the F3 peptide showed great affinity to GPC-3 positive tumor cells in vitro, ex vivo and in vivo." (PMID 34150644, 2021). "GPC3 is expressed in all tumor clusters and YAP1 is expressed in all clusters with a slight increase in Tr0." (PMID 34497364, 2021). "GPC3-CAR-T also showed tumor eliminating capabilities in HCC patient derived xenograft (PDX) models (NCT03198546) as a potential CAR-T candidate for PLC therapy." (PMID 34372912, 2021). "Here, we investigated the diagnostic accuracy of selected tumor biomarkers (i.e., AFP, PIVKA-II and GPC-3); adipokines (i.e., adiponectin and leptin) and IL-6, alone or in combination, for the discrimination between patients with or without NAFLD-related HCC." (PMID 34064999, 2021). "These organoids showed lineage specific markers in concordance with their tumor origin (pancytokeratins and glypican 3) and were depleted of myeloid and lymphoid cells as shown by the lack of CD45 stains." (PMID 34641562, 2021). "One patient had a partial response (PR) after 4 weeks, with portal vein tumor thrombus, but his body started producing the anti-GPC3 antibody after the second and third injections at 6 and 14 weeks, respectively, and he developed PD at 18 weeks." (PMID 34947886, 2021). "In conclusion, we identified a tumor-targeting peptide specific for GPC-3 with high affinity and specificity." (PMID 34150644, 2021). "CCL20, MMP14, and PCDH7 were upregulated in LUAD tumor tissues and linked to poor clinical outcomes, while BTG2, CD69, GPC3, IL7R, and NMUR1 are the opposite." (PMID 34881236, 2021). "GPC3 is a well‐known tumor marker in HCC15 and accurately predicts the recurrence after curative resection of early‐stage HCC." (PMID 33675149, 2021). "MRI imaging of efficient targeting and uptake of HepG2 cells by anti-glypican-3-antibody modification demonstrated successful particle distribution in the tumor." (PMID 34835777, 2021). "A variable degree of Glypican 3 marker cytoplasmic staining with either strong or moderate immunoreactivity was found in UESL tumor cells." (PMID 34162402, 2021). "Desirable characteristics of a radiopharmaceutical, such as rapid tumor internalization and rapid blood clearance, will be assessed to determine the ideal agent to be used for GPC3-targeted radioimmunotherapy of HCC." (PMID 34439132, 2021). "Tumor antigens, such as glypican-3 (GPC-3), and telomerase reverse transcriptase (hTERT) have been identified as potential vaccine-based immunotherapeutic targets for HCC." (PMID 34947886, 2021). "High GPC-3 expression levels were associated with CA19-9 levels over 37 IU/L (P = 0.006) and tumor size ≥ 5 cm (P = 0.005)." (PMID 34715880, 2021). "AAV-CCL19 or phosphate-buffered saline (PBS) was injected into the tumor 14 days after tumor formation, and GPC3 CAR-T cells or PBS was injected into the tail vein on the following 7 days." (PMID 34527749, 2021). "Taken together, these results demonstrated that F3 peptide showed targeting accumulation in GPC-3 positive tumor tissues in vivo." (PMID 34150644, 2021). "a recombinant adeno-associated virus 2 (AAV2) subtype carrying the CCL19 gene was used to pretreat the tumor before the Glypican-3 (GPC3) CAR-T treatment." (PMID 34527749, 2021).
tumor (continued). "Expression of tumour markers Afp, Gpc3 and Nope were significantly higher in the tumours versus the adjacent non-tumour tissues, this in keeping with the tumours being HCC (SF1F)." (PMID 34408183, 2021). "Membrane expression of GPC3, a specific marker of HCC, was designed as the target of HCC cells to determine the uptake efficiency of FITC labeled GPC3 immunoliposomes and to investigate the recognition behavior of tumor cell capture." (PMID 33726759, 2021). "Glypican-3, which is specifically expressed in cancers including WT, is being considered as a biomarker for predicting tumor recurrence." (PMID 33765954, 2021). "GPC3 showed to be overexpressed when HCC occurred, and it can also cause tumor cells to proliferate and metastasize through the Wnt signaling pathway, but it was expressed in normal liver tissues and other tissues." (PMID 34923912, 2021). "GPC-3 is highly expressed in many tumor tissues, and it is expressed in low levels in normal human tissues." (PMID 34715880, 2021). "In a patient with advanced HCC, anti-GPC3-7 × 19 CAR-T treatment resulted in complete tumor disappearance 30 days post intratumor injection." (PMID 34325726, 2021). "Another study established patient-derived xenograft (PDX) HCC models and proved that GPC3 CAR-T cells suppressed tumor growth but with varying efficacy due to different expressions of PDL1 on tumor cells." (PMID 34675942, 2021). "Given its high tumor-to-liver ratio, GPC3 is supposedly suitable for targeted imaging approaches in HCC." (PMID 34359547, 2021). "ImmunoPET tracers using intact anti-GPC3 antibodies can achieve high specific uptake at the tumor sites." (PMID 34439132, 2021). "An animal experiment demonstrated that the synergistic anti-tumor effects depended on increased GPC3-induced CTL though the combination of PD-1/PD-L1 blockade and GPC3 peptide vaccine." (PMID 34975896, 2021). "In LUAD samples, GPC3 expression was significantly correlated with pathologic N, pathologic T, gender, and tumour stage." (PMID 34112123, 2021). "In a reconstituted mouse model, ERY974 was found to have excellent antitumor activity against diverse types of GPC3-expressing tumor cells." (PMID 34922633, 2021). "Immunohistochemically, this tumor tested positive for vimentin, CD 99, glypican-3, synaptopysin, WT-1, CK, and EMA." (PMID 34054966, 2021). "The expression of the tumor markers in both models was similar, with an increase in the mRNA levels of Ly6d, Afp, Gpc3, Birc5, and Lyve1 being higher in DEN-treated WT mice compared to MUP-uPA, while that of Cd44 was comparable in both models." (PMID 34439245, 2021). "Glypican-3 (GPC3) targeted Fe3O4 core/Au shell nanocomplex for fluorescence/MRI/photoacoustic imaging-guided tumor photothermal therapy." (PMID 33710819, 2021). "Glypican-3 (GPC3), a carcinoembryonic antigen ideal for immunotherapy target, has been studied extensively as an anti-tumor vaccine of HCC." (PMID 34975896, 2021). "An evident infiltration of NK-92/9.28.ζ cells, a decreased tumor proliferation and an increased tumor apoptosis were observed in the GPC3+ HCC xenografts." (PMID 32707982, 2020). "To minimize any on-target/off-tumor toxicity, we use logic-gated (log) GPC3–synNotch-inducible CD147-CAR to target HCC." (PMID 32968061, 2020). "As expected, tumor burden from the CD147+GPC3high HepG2 inoculated mice treated with GPC3-synNotch-inducible CD147-CAR-NK-92MI cells was reduced, compared with that of mice bearing CD147+GPC3low HepG2 tumor cells." (PMID 32968061, 2020). "In an in vivo experiment, a fluorescent-labeled GPC3 aptamer displayed excellent potential as a tumor-targeting imaging probe." (PMID 33080969, 2020). "GPC3 is not only expressed on the surface of tumor cells, but also released into peripheral in soluble form (sGPC3)." (PMID 32127929, 2020).